CASP1 (caspase 1)
Diseases named in the same sentence as CASP1 in open-access papers (continued):
Sharing a sentence is not in itself a finding about the gene and the disease.
infection (continued). "In that study, MCC950 treatment and caspase-1/11 deficiency was able to phenocopy Nlrp3−/− mice during infection." (PMID 31586037, 2019). "Mice lacking either caspase-11 or GSDMD were significantly more susceptible to infection with B. abortus than caspase-1 knockout or wild-type animals." (PMID 30589883, 2018). "The bacterial burdens in different organs were measured at different time points post-infection (p.i.)and in mice infected using different doses and revealed the relative susceptibility of Casp1-/-, Casp11-/-, and Casp1-/-/Casp11-/- mice." (PMID 29791511, 2018). "Mice deficient of caspase-1 or caspase-11 are more susceptible to infection with B. pseudomallei or the closely related B. thailandensis." (PMID 29791511, 2018). "Altogether, our results clearly demonstrate that the deficiency in caspase-1/11−/− worsens the induction of the cytotoxic response during the infection with this parasite." (PMID 29774028, 2018). "Consistent with this interpretation, caspase-1-deficient mice are more susceptible to infection and to death when challenged with Salmonella." (PMID 29881383, 2018). "To address this issue, we isolated pDCs from YM-infected WT and gene deficient (Aim2−/−, Nlrp3−/−, Casp1−/−, Il1r1−/−, and Mavs−/−) mice at 18 h post YM infection and assessed mRNA expression levels of SOCS1, IFN-α and IFN-β." (PMID 30470758, 2018). "Accordingly, macrophages and mice deficient in Asc/Casp1/11-/- were more susceptible than Casp1/11-/- and as susceptible as Nlrc4-/- for the restriction of infection." (PMID 28771586, 2017). "This control was associated with IL-1β and IL-18 secretion induced by caspase-1 activity starting at an early phase of infection." (PMID 28740491, 2017). "In the conclusion, our results indicated that RIP3 deficiency can protect mice from the infection of influenza H7N9 virus by downregulating caspase 1/IL1β signaling, which provided evidence of the RIP3 involved necroptosis independent manner." (PMID 28423682, 2017). "The results showed that Caspa was indeed able to rescue the infection susceptibility but only partially caspase-1 activity of Caiap-deficient larvae." (PMID 29123523, 2017). "Infections performed with L. gratiana and L. micdadei indicated that Asc/Casp1/11-/- macrophages were as susceptible as Nlrc4-/-, whereas Casp1/11-/- cells were partially restrictive." (PMID 28771586, 2017). "The results showed that Cxcr2 deficiency resulted in higher susceptibility to the infection and, interestingly, it fully overcame both Gbp4- and Asc- induced infection resistance and caspase-1 activity." (PMID 27363812, 2016). "So, we next infected Gbp4-deficient fish with WT ST and found an increased susceptibility to the infection compared with their control siblings and impaired caspase-1 activity in response to the infection." (PMID 27363812, 2016). "siRNA knockdown experiments also showed that loss of ASC significantly reduced the induction of caspase-1 activity and IL-1β secretion following infection with M. bovis." (PMID 27043315, 2016). "Others have reported the activation of NLRP3 complexes and recruitment of caspase-1, together with IL-18/IL-1β release, in primary microglia and in macrophages stimulated by infection-associated agents." (PMID 28096568, 2016). "After the discovery of caspase-1 deficient mice being accidentally caspase-1/caspase-11 double knockout, the importance of caspase-1 for restriction of L. pneumophila in murine infections had to be reevaluated." (PMID 27148204, 2016). "These animals were highly susceptible to infection and all succumbed within a few days, similar to caspase-1/11 deficient mice." (PMID 27911947, 2016). "12h infection experiments with caspase-1/11-deficient animals and their littermate controls verified that this is indeed the case." (PMID 27341123, 2016).
infection (continued). "Of note, quiescent CD4 T-cells are particularly susceptible to death by caspase-1 mediated pyroptosis induced by accumulation of incomplete HIV reverse transcripts resulting from abortive infection." (PMID 25333710, 2014). "Infection of caspase-1 deficient BMDMs with live B. pertussis induced release of IL-1β into the culture supernatant, although at significantly lower levels than wild-type cells." (PMID 25198773, 2014). "SipB associates with the proapoptotic protease caspase-1, and induces apoptosis of macrophages possibly permitting bacterial dissemination during infection." (PMID 23950998, 2013). "Caspase-1 activation and the processing/release of IL-1β were completely inhibited in the infection of NLRP3- and ASC-deficient BMMs, whereas inhibition was marginal in NLRC4-deficient cells." (PMID 23357873, 2013). "The NLRP3−/− and caspase-1−/− macrophages demonstrated a marked deficiency in the control of infection, as the number of amastigotes and the frequency of infected cells were even higher than in the susceptible MyD88−/− macrophages." (PMID 24098823, 2013). "During infection with pathogenic bacteria, assembly and activation of the inflammasome result in caspase-1 activation and IL-1β secretion, which are critical for an effective immune response." (PMID 22558425, 2012). "This “low MOI" infection procedure has previously been shown to cause cytotoxicity, activation of caspase-1, and high level secretion of IL-1β in macrophages." (PMID 22563435, 2012). "We have recently reported that the intracellular infection of macrophages with B. cenocepacia K56-2 is associated with caspase-1-dependent release of IL-1β." (PMID 22848580, 2012). "Mice deficient in caspase-1 or the end product of inflammasome activation, namely IL-1β and IL-18, have higher bacterial load and succumb earlier upon infection with S. Typhimurium." (PMID 23055923, 2012). "Wild-type and congenic caspase 1 knockout C57BL/6 mice were equally susceptible to lethal infection with Y. pseudotuberculosis ectopically expressing YopP." (PMID 22563435, 2012). "Infection ofIKKβ-deficient macrophages with Y. pestis confirmed that thiskinase has an important role in negatively regulating caspase-1 activation." (PMID 21533069, 2011). "Caspase-1 is activated within a large multi-protein complex, termed the inflammasome, which is triggered by several danger-, stress- and/or infection-associated signals leading to caspase-1 cleavage and activation." (PMID 19652710, 2009). "The protein expression of seven proteins (CD8A, ST1A1, AXIN1, FGF-5, MMP-10, HGF, SIRT2) was significantly decreased and the protein expression of two proteins (MMP-1, TNFRSF9) was significantly increased in caspase-1-deficient cells compared to Cas9 cells following HK1651 infection." (PMID 40137780, 2025). "Notably, infection with a pneumolysin-deficient mutant conferred strong protection against disease aggravation caused by macrophage depletion, whereas caspase-1 inhibition - despite its known immunosuppressive effects in experimental PM - did not." (PMID 40988032, 2025). "Furthermore, mice deficient in caspase-1 were also more susceptible to infection with B. pseudomallei than the wild-type mice." (PMID 40627773, 2025). "Additionally, caspase-1 and caspase-11 deficient mice are more susceptible to infection with B. pseudomallei or the closely related B. thailandensis." (PMID 40627773, 2025). "Although, during in vivo T. gondii infection, it is unclear whether direct invasion of the parasite and/or an infection-associated trigger is necessary for caspase-1 activation." (PMID 39446964, 2024). "To test this hypothesis, we performed a rescue experiment, where we administered recombinant IL-18 (rIL-18) at 10μg/kg or PBS to Cx3cr1+Casp1 deficient mice at 1 hour post-infection and on days 1, 3, 5, and 7 post-infection." (PMID 39446964, 2024). "In Caspase-1 deficiency macrophages, pyroptosis diminished during infection." (PMID 37457695, 2023).
infection (continued). "In addition, M1-, and to a lesser extent M2-differentiated caspase 1-deficient THP-1 cells also produced IL-1β in response to infection." (PMID 36851476, 2023). "Excluding infection, injurious mechanical ventilation only could induce AM pyroptosis and be associated by caspase-1 in our study." (PMID 35462787, 2022). "The data suggest that ExoU differentially affects NLRC4 inflammasome activation early in infection, causing a transient delay in caspase-1 release to the culture medium, whereas the effects of ExoU can be observed in enriched mito-MAM fractions at later time points." (PMID 35130452, 2022). "In effect, caspase-1 released to the extracellular milieu may control inflammatory responses to infection, whereas mitochondrion-associated caspase-1 may control cellular behaviors such as metabolism and mitochondrial function." (PMID 35130452, 2022). "Casp-1 deficiency (Casp-1−/−) caused a significant decrease in IL-1β production (green lines), while IL-1α secretion as well as the level of cell death remained unaffected during infection with all three Rickettsia spp." (PMID 35130729, 2022). "To further investigate the mechanisms responsible for Caspase-1 activation by S. Enteritidis GalE protein, we monitored the activation of Caspase-1 in Nlrp3−/− and Nlrc4−/−-deficient BMDMs in response to infection with different mutant strains of S. Enteritidis." (PMID 35630356, 2022). "To test such hypothesis, we first analysed caspase-1 cleavage, caused by inflammasome activation, upon infection of BMDMs with wild-type or ΔoatA mutant strain by western blotting." (PMID 36128739, 2022). "Furthermore, the protein levels also showed that pyroptosis-associated caspase-1 expression and apoptosis-associated caspase-3 activation were significantly induced after infection." (PMID 34831405, 2021). "However, mice deficient in PANoptosis were more susceptible to lethal infection than either Gsdmd−/− or Casp1/11−/− mice, suggesting that pyroptosis and apoptosis both mediate protection during B. thailandensis infection." (PMID 34154417, 2021). "Because B. thailandensisvgrG5ΔCTD was not efficiently cleared from Casp8/Ripk3/Casp1/11−/− BMDMs, we hypothesized that Casp8/Ripk3/Casp1/11−/− mice may be more susceptible to infection than WT mice." (PMID 34154417, 2021). "During infection of exogenous pathogenic microorganism, many types of murine Gbps and human Gbp2 and Gbp5 can trigger the host cells’ pyroptosis by activating inflammasome complex containing caspase-1 or caspase-4." (PMID 32731337, 2020). "Among the infection-specific ISGs upregulated during ΔHA-Cre infection are genes associated with apoptosis (Ripk2, Casp1, Ifi27, Pmaip1) and E3 ubiquitin ligases and proteasome genes, some of which are known to be involved in MHC-I antigen processing (Neurl3, Rnf19b, Psmb9)." (PMID 32790753, 2020). "Furthermore, infection of double-deficient (RIPK3–/– Casp-1/11–/–) mice with ST-OVA results in a higher frequency of IFN-γ-producing CD8+ T cells." (PMID 32328060, 2020). "In addition, differences in host susceptibility to IL-1β, IL-18, and caspase-1-deficient mice during infection have been reported." (PMID 29616195, 2018). "Furthermore, Caiap crispant larvae also showed higher susceptibility to ST infection and reduced caspase-1 activity upon infection than their WT siblings." (PMID 29123523, 2017). "Similarly, in WT and caspase-1/caspase-11 (casp-1/11)-deficient macrophages, infection with VSV or treatment with etoposide results in cleavage of endogenous DFNA5 into the necrotic N-terminal fragment and induction of secondary necrosis." (PMID 28045099, 2017). "However, mice deficient for IL-1β, IL-18 or caspase 1 were as susceptible as wild-type mice to both blood stage and sporozoite PbA-infection." (PMID 28448579, 2017).
infection (continued). "Decreased MAC formation may be associated with reduced IL-1β production through activation of caspase 1, followed by inflammasome formation in the recipients; this might further contribute to the high risk of infection in these recipients." (PMID 27063552, 2016). "However, following lethal infection with Francisella, IL-1r-, Caspase-1/11-, Asc- and Aim2-deficient mice exhibited increased susceptibility as expected, while Nlrp3-deficient mice were more resistant." (PMID 27926940, 2016). "The activation of caspase-1 has been linked to infection-induced cell death and apoptosis." (PMID 24643116, 2014). "In addition, in a mouse model of infection with C. muridarum, wild-type and caspase-1 deficient mice equally controlled the replication of the bacteria in vivo." (PMID 24324933, 2013). "However, caspase-1−/− mice are more susceptible to some infections than IL-1β−/−IL-18−/− mice, underscoring the importance of additional caspase-1 substrates that alter the immune response." (PMID 24367258, 2013). "Asc- and caspase-1-deficient mouse fibroblasts are resistant to infection by C. trachomatis." (PMID 24324933, 2013). "We detected increased DEVDase activity upon infection of caspase-1 deficient BMDM." (PMID 22807671, 2012). "Thus, Abdul-Sater and coworkers demonstrated that infection by an intracellular bacterial pathogen led to the efflux of intracellular K+, which in turn, causing ROS production and caspase-1 activation in epithelial cells." (PMID 22844468, 2012). "Additionally, Casp8/Ripk3/Casp1/11−/− mice, which are deficient in PANoptosis, allow the study of the combined roles of pyroptosis, caspase-8-dependent apoptosis, and necroptosis during infection." (PMID 34154417, 2021). "Inflammasome is a functional complex assembled in response to infection or tissue injury, which senses signals from pathogen-associated molecular patterns (PAMPs) or danger-associated molecular patterns (DAMPs) to generate active caspase-1, which converts IL-1β into its mature active form." (PMID 34771641, 2021). "Given our observation that PANoptosis-deficient BMDMs (Casp8/Ripk3/Casp1/11−/−) displayed distinct cell death activation kinetics during B. thailandensis infection, we biochemically examined the activation of pyroptotic, apoptotic, and necroptotic pathways at 24 h of infection." (PMID 34154417, 2021). "Thus, RSV may also encode protein(s) that disrupt caspase-1 activity during infection, thus triggering an ASC-NLRP3 inflammasome mediated activation of the necroptotic pathway." (PMID 32854254, 2020). "Furthermore, GSDMD-independent secondary necrosis appears to contribute to the clearance of bacterial infection, as it could be shown that Gsdmd−/− mice are less susceptible to infection with Francisella novicida compared with Casp1- or Aim2-deficient animals." (PMID 32345661, 2020). "The natural immune response that occurs as an early response to infection causes the release of proinflammatory cytokines such as interleukin 1, interleukin beta, and interleukin 18 from macrophages in the cytoplasm, which in turn induce caspase-1-dependent cell death." (PMID 31245979, 2019). "Indeed, Caspase-1/11- and Aim2-deficiency is associated with ineffective clearance of Ft, as evidenced by bacterial burdens comparable or higher than control mice later in infection." (PMID 27926940, 2016). "Infection of larvae expressing a RNA encoding a fusion between zebrafish pro-IL-1β and GLuc (zfiGLuc) resulted in increased luciferase activity independently of Asc (assayed in Asc-deficient fish) and caspase-1 activity (assayed in the presence of caspase-1 or pan-caspase inhibitors)." (PMID 27363812, 2016). "With the realization that the Caspase-1 KO was in fact a Caspase-1/Caspase-11 double knockout, and the elucidation of the role of Caspase-11 in non-canonical inflammasome activation, Caspase-11-deficient mice were predicted to result in more bacterial spread due to diminished control of infection." (PMID 24381573, 2013).
infection (continued). "However, a role for pyroptosis for caspase-1-dependent susceptibility to infection is still speculative." (PMID 24324933, 2013). "Of note, caspase-1-deficient mice displayed reduced inflammatory damage in the urogenital tract, suggesting that inflammasome activation may contribute to the pathology of infection by Chlamydia." (PMID 24324933, 2013). "Besides, results also indicated that the difference of recombinant protein production between Sf-caspase-1-repressed and normal cells may be caused by the diverse cellular states that occur during the middle phase of the infection process." (PMID 23134743, 2012). "For example, caspase-1/4/5/8/11 are known to cleave GSDMD, which results in GSDMD-mediated pyroptosis, and under pathogenic infection, caspase-1 cleavage of GSDMD is the most common occurrence of GSDMD-mediated pyroptosis." (PMID 40503916, 2025). "Treatment with 100 mg/kg BW baicalin also attenuated cleaved caspase-1 protein expression compared with the infection group (p < 0.01)." (PMID 40305201, 2025). "We further examined ASC oligomerization, an indicator of inflammasome activation, in BMDMs deficient in caspase-1, caspase-11, or NLRP3 upon infection with K. pneumoniae." (PMID 40034692, 2025). "We then monitored vital pulmonary signs of infection in the Casp1-/- and Casp1+/+ mice at 12 hours after E. coli challenge." (PMID 40359428, 2025). "IP-10, IFNL1, IFNB1, and CASP1 gene expressions were significantly induced by Delta infection, whereas Remdesivir treatment prevented it efficiently with levels similar to non-infected cultures." (PMID 40142465, 2025). "Both processes are regulated by the inflammasome, a cytosolic multiprotein complex with the effector CASP1, which can activate myelopoiesis and pyroptotic cell death under homeostatic conditions and during infection." (PMID 41360763, 2025). "The mRNA expression levels of NLRP3 and Caspase 1 in the infection group were raised compared to the control group (p < 0.001)." (PMID 40427615, 2025). "For example, caspase-3 (apoptotic) and caspase-1 (pyroptotic) can be activated simultaneously in response to severe cellular stress or infection." (PMID 40770673, 2025). "We continued to investigate the role of caspase-1 and caspase-4 in the release of chemokines from gingival epithelial cells after infection with HK1651 for 24 h." (PMID 40137780, 2025). "The NLRP3 inflammasome is composed of NLRP3, ASC, and pro-caspase-1, regulating the activation of caspase-1 and following the release of IL-1β and IL-18 from innate immune cells during infection or damage." (PMID 40872501, 2025). "The NLRP3 and caspase-1 mRNA levels were increased in the infection group compared with the control group (p < 0.001)." (PMID 40305201, 2025). "This reduction was confirmed at the protein level in HT29 cells, with a significant decrease in IL1β and CASP1 expression observed 2 h post-infection (p < 0.05) and further downregulation at 24 h post-infection (p < 0.01)." (PMID 39943201, 2025). "Caspase-1 is required for inflammasome responses and control of intracellular Salmonella replication early during infection." (PMID 40162563, 2025). "Further analysis of expression patterns indicated that caspase-1 pro-forms and active forms were often co-upregulated following infection." (PMID 40563885, 2025). "For double-positive cells, an elevation in the quantity of CD3 and caspase-1 double-positive cells subsequent to HP-PRRSV infection was discerned mainly in the HLNs, tonsils, and spleen." (PMID 40143222, 2025). "GSDMD activation succeeded GSDME activation, with the p30 subunit of GSDMD, as well as caspase-1 cleavage, observed in the cell supernatants from 18 h or 36 h following Brazil/78 and HKx31 infection." (PMID 40481027, 2025). "E. coli’s CNF1 toxin triggers protective immunity in both Drosophila and murine infection models, but in mice specifically this response was shown to be caspase-1–dependent." (PMID 39883598, 2025).